PSMD2 (proteasome 26S subunit ubiquitin receptor, non-ATPase 2)
Diseases named in the same sentence as PSMD2 in open-access papers (continued):
Sharing a sentence is not in itself a finding about the gene and the disease.
lung adenocarcinoma (continued). "In the present study, our results showed that the mRNA and protein expression of PSMD2 is elevated in lung adenocarcinoma tissues." (PMID 35754829, 2022). "Paired t-test analysis showed that PSMD2 mRNA expression level in lung adenocarcinoma (n = 57) were significantly upregulated relative to normal lung tissues (n = 57) (7.156 ± 0.662 vs. 6.512 ± 0.177, p < 0.001)." (PMID 35754829, 2022). "Our results confirmed that high expression of PSMD2 is correlated with poor prognosis and PSMD2 is an independent prognostic biomarker for lung adenocarcinoma patients." (PMID 35754829, 2022). "PSMD2 expression was positively correlated with cell cycle, DNA damage, and DNA repair, while negatively correlated with quiescence in lung adenocarcinoma." (PMID 35754829, 2022). "Our findings suggest that PSMD2 expression is correlated with immune cell infiltration and raise the possibility that PSMD2 can be a potential immunotherapy target in lung adenocarcinoma." (PMID 35754829, 2022). "Overall, these results indicate that protein expression of PSMD2 is increased in lung adenocarcinoma tissues." (PMID 35754829, 2022). "Another study reported that overexpression of PSMD2 predicted a poor prognosis for lung adenocarcinoma patients." (PMID 27966459, 2017). "Taken together, these results indicate that PSMD2 expression is correlated with most TILs in lung adenocarcinoma, further suggesting that PSMD2 may play an important role in the lung adenocarcinoma microenvironment." (PMID 35754829, 2022). "In light of the PrognoScan database, Kaplan-Meier curves, and multivariate Cox analysis, our results confirmed that high expression of PSMD2 is correlated with poor prognosis and PSMD2 is an independent prognostic biomarker for overall survival of lung adenocarcinoma patients." (PMID 35754829, 2022). "Here, we examined the prognostic and immunological role of PSMD2 in lung adenocarcinoma." (PMID 35754829, 2022). "Moreover, we analyzed the correlation between PSMD2 expression and the clinicopathological factors of lung adenocarcinoma patients." (PMID 35754829, 2022). "Indeed, the proteasomal subunit, PSMD2, has prognostic significance in patients with bladder urothelial carcinoma and lung adenocarcinoma." (PMID 36498916, 2022). "On the whole, these results suggest that PSMD2 may regulate the level of tumor-infiltrating immune cells to affect lung adenocarcinoma progression." (PMID 35754829, 2022). "Moreover, immune infiltration analysis suggested that PSMD2 expression had a significant correlation with the level of tumor-infiltrating immune cells, further suggesting a specific role for PSMD2 in the immunological interactions in lung adenocarcinoma." (PMID 35754829, 2022). "Highly expressed PSMD2 and SMD14 were greatly related to lymph node metastases and TNM phase of lung adenocarcinoma, while high expression of PSMD2, PSMD7, PSMD14 were linked to poor OS and/ or disease-free survival (DFS) among these patients." (PMID 37337223, 2023). "The disease-specific survival of lung adenocarcinoma patients with higher PSMD2 expression was also significantly shorter than those with lower PSMD2 expression (59.9 months vs. not available, p = 0.004)." (PMID 35754829, 2022). "In addition, there are some genes in other modules that can have very important roles in lung adenocarcinoma, namely DLGAP5, BIRC5, PSMD2, Src, TTK, SENP2, PSMD2, DOK2, FUS among others." (PMID 23874428, 2013).
lung carcinoma (6 papers, 2018 to 2022). "PSMD2 has also been shown to be associated with the acquisition of metastatic phenotypes and poor prognosis in various lung cancers." (PMID 35711913, 2022). "A previous study has shown that PSMD2 was overexpressed in lung cancer and patients with higher expression of PSMD2 were correlated with poorer prognosis." (PMID 35754829, 2022). "Interestingly, among the top 6 co-expressed genes of PSMD2, the EIF4G1 and TUBA1C were reported to be related to immune infiltration in lung cancer, and EIF4G1 is significantly associated with the PD-L1 expression." (PMID 36505799, 2022). "Furthermore, PSMD2 reduces proliferation and induces apoptosis in lung cancer cells, and the overexpression of PSMD2 could stimulate cell growth in SMMC-7721 and NIH-3T3 cells." (PMID 31703613, 2019). "While some of the 70 HKGs (e.g., PSMD2) have been identified by other genome-wide association studies as relevant in single subtypes of lung cancer development (AD), many have not been fully examined, adding to the list of possible targets for therapeutic development." (PMID 29761043, 2018).
COVID-19 (5 papers, 2022 to 2024). A disease caused by infection with severe acute respiratory syndrome coronavirus 2. "Through unbiased KEGG pathway analysis of DEGs between Fga−/− and WT plasma-stimulated microglia, we identified the 12 top pathways induced by fibrinogen, including ROS (for example, Hmox1, Cox7a2, Slc25a5), COVID-19 (for example, Ccl12, Rps8, Rpl35) and AD (for example, Atp5e, Psmd2, Tubb5)." (PMID 37291385, 2023). "Fifteen proteasomal proteins showed an increase in serum levels of COVID-19 patients, most notably PSMA7, PSME1, PSMB3, PSMA4 and PSMA5, whereas PSMD2 was the only one with decreased levels." (PMID 37739942, 2023).
colorectal cancer (4 papers, 2019 to 2023). A primary or metastatic malignant neoplasm that affects the colon or rectum. "In colorectal cancer, PSMD2 can facilitate the degradation of diverse Ras-related GTPase and then inhibit cell proliferation and affect the expression of cell-cycle protein via blocking NF-kappaB signaling." (PMID 35754829, 2022). "The biological function of asporin inside cancer cells was largely neglected until it was found that asporin interacts with intracellular Smad2/3 and PSMD2 to facilitate gastric and colorectal cancer progression." (PMID 31608236, 2019). "PSMD2 also reduces the protein levels of a variety of Ras-related GTPase, including DIRAS family GTPase 2 (DIRAS2) through the proteasome-mediated pathway and subsequently blocks the NF-κB signalling pathway and suppresses cell proliferation in colorectal cancer." (PMID 37875476, 2023).
bladder urothelial carcinoma (3 papers, 2022 to 2023). "Based on the result of univariate and multivariate analysis, PSMD2 has been identified as an independent prognostic biomarker for overall survival in bladder urothelial carcinoma." (PMID 35754829, 2022). "In urothelial bladder carcinoma, PSMD2, PSMD3, PSMD4, PSMD8, and PSMD11 genes are overexpressed." (PMID 36934426, 2023).
lymph node metastases (3 papers, 2022 to 2023). "On the whole, these results indicate that PSMD2 had a significant correlation with T stage, lymph node metastases, and high TNM stage." (PMID 35754829, 2022).
nasopharyngeal carcinoma (3 papers, 2023 to 2025). A carcinoma arising from the nasopharyngeal epithelium. "Moreover, it has been shown that DNAJA4 inhibits invasion and metastasis of nasopharyngeal carcinoma through PSMD2-mediated proteasomal degradation of MYH9." (PMID 39550407, 2024). "For example, in nasopharyngeal carcinoma, DNAJA4 directly interacts with MYH9, recruiting PSMD2 to promote MYH9 ubiquitination and degradation, thereby inhibiting nasopharyngeal carcinoma migration and EMT." (PMID 39988672, 2025).
Bladder Cancer (2 papers, 2022 to 2026). "PSMD2 was remarkably overexpressed in most cancer types, including bladder cancer." (PMID 36505799, 2022).
thyroid cancer (2 papers, 2022 to 2025). "Additionally, two recent studies reported that the gene signature based on the PSMD2 expression is tightly linked with prognoses and immune infiltrates in HNSCC and thyroid cancer." (PMID 36505799, 2022).
brain tumour (1 paper, 2024). "Of note, ANXA1, ANXA2, GNAS, HSP90AA1, HSP90AB1 and PSMD2, were highly abundant in EVs captured from GBM neurosurgical aspirates and in Pre-OP GBM uEVs here, implicating a potential brain tumour diagnostic utility for TRiC subunits and their interacting partners." (PMID 38212481, 2024).
breast tumor (1 paper, 2021). "Immunohistochemical (IHC) images revealed dense distributions of PSMD2 and PSMD4, while the other PSMDs, including PSMD1, PSMD2, PSMD3, PSMD7, PSMD12, and PSMD14, were moderately distributed in breast tumor samples." (PMID 34839279, 2021).
diabetes (1 paper, 2017). "Furthermore, other genes in this region, including PSMD2 itself, could be linked to diabetes pathology." (PMID 28253288, 2017).
esophageal cancer (1 paper, 2023). A primary or metastatic malignant neoplasm involving the esophagus. "Analysis of the TCGA esophageal cancer dataset (ESCA) also revealed significantly higher PSMD2 expression in tumors than in normal tissues." (PMID 36998052, 2023).
esophageal squamous cell carcinoma (1 paper, 2023). Esophageal squamous cell carcinoma (ESCC) is a type of esophageal carcinoma (EC) that can affect any part of the esophagus, but is usually located in the upper or middle third. "However, the detailed role of PSMD2 in autophagy and its relationship to tumorigenesis in esophageal squamous cell carcinoma (ESCC) remain unknown." (PMID 36998052, 2023).
frontotemporal dementia (1 paper, 2022). Frontotemporal dementia (FTD) comprises a group of neurodegenerative disorders, characterized by progressive changes in behavior, executive dysfunction and language impairment, as a result of degeneration of the medial prefrontal and frontoinsular cortices. "Association of SOD1 with module-1 proteins (PSMD2, ADRM1, RAD23A) were involved in ALS15-type with or without Frontotemporal dementia." (PMID 34918006, 2022).
gastric cancer (1 paper, 2022). A primary or metastatic malignant neoplasm involving the stomach. "Recently, high expression of several of these PSM genes (e.g. PSMA1, PSMB4, and PSMD2) has been correlated with poor prognosis in a number of cancer types, including breast-, lung-, and gastric cancer." (PMID 36123629, 2022).
glioma (1 paper, 2023). A benign or malignant brain and spinal cord tumor that arises from glial cells (astrocytes, oligodendrocytes, ependymal cells). "The mRNA expression of PSMD1/4/5/8/9/10/11/12 was significantly correlated with glioma grade, while the mRNA expression of PSMD2/3/6/7/13/14 was not correlated with glioma grade." (PMID 37485655, 2023).
liver fibrosis (1 paper, 2014). "Therefore, PSMD2 might be involved in the generation of liver fibrosis." (PMID 25280538, 2014).
ovarian carcinoma (1 paper, 2023). A malignant neoplasm originating from the surface ovarian epithelium. "The expression levels of PSMD8/14 mRNA in ovarian cancer tissues were significantly higher than those in normal ovarian tissues, and the expression levels of PSMD2/3/4/5/8/11/12/14 mRNA were associated with prognosis." (PMID 37349676, 2023).
ovarian serous carcinoma (1 paper, 2023). "Up-regulation of PSMD4/8/14 mRNA expression was associated with poor OS, and the up-regulation of PSMD2/3/5/8 mRNA expression was associated with poor PFS in patients with ovarian serous carcinomas." (PMID 37349676, 2023).
pancreatic tumor (1 paper, 2025). "Systematic evaluation of PSMD1-14 expression revealed significant upregulation (p<0.05) of PSMD1, PSMD2, PSMD3, PSMD4, PSMD7-PSMD14 transcripts in pancreatic tumor tissues compared with adjacent normal controls, with the notable exception of PSMD6 which demonstrated reduced mRNA expression." (PMID 40182048, 2025).
type 2 diabetes (1 paper, 2017). "In summary, we observed a significant association between the PSMD2 gene region and type 2 diabetes in women of African ancestry in a gene-based analysis." (PMID 28253288, 2017). "Gene-based analyses of common variants in the vicinity of β-catenin destruction complex genes identified an association between the PSMD2 gene region and type 2 diabetes in 2632 AA cases and 2596 AA controls." (PMID 28253288, 2017). "Genetic variants comprising the optimal models for PSMD2 and TCF7L2: associations with risk of type 2 diabetes in the BWHS." (PMID 28253288, 2017).
tumor (17 papers, 2017 to 2026). "In the present study, we have investigated the tumor-promoting roles of PSMD2 in the context of autophagy in ESCC." (PMID 36998052, 2023). "Our findings that the depletion of ATG7 abrogates the inhibitory effects of PSMD2 knockdown on ESCC cell proliferation indicate that the tumor-promoting roles of PSMD2 in ESCC depends on its activity to inhibit autophagy." (PMID 36998052, 2023). "In this study, we found that the overexpression of PSMD2 is correlated with tumor aggression and poor survival of patients with ESCC." (PMID 36998052, 2023). "And the IHC score of PSMD2 was significantly correlated with tumor stage and lymph node invasion (P = 0.001, 0.014)." (PMID 37864031, 2023). "Tumor-Immune system interaction database (TISIDB) was performed to verify the correlation between PSMD2 expression and tumor-infiltrating lymphocytes (TILs)." (PMID 35754829, 2022). "Functioning as a component of the proteasome, PSMD2 was reported to play a vital role in tumor progression." (PMID 35754829, 2022). "In the present study, we identified a novel way in which PSMD1 and PSMD2 promote tumor cell proliferation—namely, via increasing cellular FA and lipid synthesis." (PMID 31703613, 2019). "Recent studies indicate that knockdown of PSMD1 and/or PSMD2 is able to suppress tumor cell proliferation." (PMID 31703613, 2019). "Our findings provide new insight into the regulatory roles of PSMD1 and PSMD2 in tumor cell proliferation via regulating lipid metabolism." (PMID 31703613, 2019). "Briefly, the knockdown of PSMD1 and/or PSMD2 decreases the formation of cellular lipid droplets, the provider of the energy and membrane components for tumor cell proliferation." (PMID 31703613, 2019). "To further confirm whether PSMD2 is critical to DIRAS2-mediated tumor-suppression activity, we performed a PSMD2 rescue experiment, and our functional study revealed that PSMD2 OV reversed DIRAS2-inhibited cellular proliferation." (PMID 35173535, 2022). "Elevated PSMD2 expression was correlated with advanced tumor grade and pathologic stage." (PMID 36505799, 2022). "Moreover, PSMD2 expression had a significant correlation with the level of tumor-infiltrating immune cells." (PMID 35754829, 2022). "Therefore, as the important subunits of the 26S proteasome, PSMD1 and PSMD2 also regulate tumor cell growth." (PMID 31703613, 2019). "Among these, key genes including TMEM106C, ECT2, PSMD2, STIL, and TTK showed significant upregulation in tumor tissues, and their high expression may be closely associated with abnormal activation of tumor stem cells, cell cycle regulation, and enhanced self-renewal capacity." (PMID 40766320, 2025). "We also noted that the tumor-suppressing activity of DIRAS2 could be overridden by PSMD2." (PMID 35173535, 2022). "PSMD1 and PSMD2 could be potential therapeutic targets for this type of tumor." (PMID 31703613, 2019). "Comprehensive differential expression analysis between normal and tumor tissues revealed complex regulatory patterns of stem cell marker genes, with key genes such as TMEM106C, ECT2, PSMD2, STIL, and TTK showing significant upregulation in tumor tissues." (PMID 40766320, 2025). "We demonstrate that the overexpression of PSMD2 promotes ESCC cell growth by inhibiting autophagy and is correlated with tumor progression and poor prognosis of ESCC patients." (PMID 36998052, 2023). "This study provides new insights into the PSMD1/PSMD2 regulatory mechanism in HCC cell proliferation and provides a potential novel therapeutic strategy for lipid-rich tumor." (PMID 31703613, 2019). "Analysis of thousands of tumor samples from The Cancer Genome Atlas (TCGA) reported an increased expression of proteasomes such as PSMB6, PSMB7, and PSMD2 in most cancer types." (PMID 31877708, 2019).
tumor (continued). "The results indicated that high expression levels of PSMD1 and PSMD2 decrease the survival rate of LIHC, which corresponds to our study where PSMD1 and PSMD2 increased the LD content and promoted tumor cell proliferation." (PMID 31703613, 2019). "Combined bioinformatics and experimental analyses reveal that PSMD2 downregulates chemokine (C-X-C motif) ligand 14 (CXCL14) expression and secretion via the MAPK pathway, thereby remodeling the immune microenvironment and driving tumor progression." (PMID 41930182, 2026). "The results of IHC assay revealed that MYH9 was downregulated in DNAJA4-overexpressing tumours, while PSMD2 expression had no obvious change." (PMID 37875476, 2023). "Studies have reported that PSMD2 is a non-ATP subunit of the 19S proteasome complex and is highly expressed and correlated with tumor stage in NSCLC." (PMID 37864031, 2023). "As far as we know, no study has reported this regulatory function of PSMD1 and PSMD2 in tumor cells." (PMID 31703613, 2019). "Bortezomib could target PSMD2, PSMB1 and PSMB5 to inhibit the proteasome degradation of cell cycle check points, to block cell proliferation and tumor growth of NSCLC, which was potential optional drug for NSCLC patients with different driven mutations or with TKI resistance." (PMID 37864031, 2023). "Dual functions of PSMD2 might explain why the sole inhibition of the UPS system or autophagy is not effective in cancer treatment but instead promotes tumor progression." (PMID 36998052, 2023). "However, the way in which PSMD1 and PSMD2 regulate tumor cell proliferation is not totally clear." (PMID 31703613, 2019). "The 26S proteasome non-ATPase regulatory subunit (PSMD) 2 (PSMD2), PSMD7, and PSMD14 proteins participate in the ubiquitin-proteasome system, which plays a potential role in the proliferation and progression of tumor cells." (PMID 37350936, 2023).